CXCL10 (C-X-C motif chemokine ligand 10)
Diseases named in the same sentence as CXCL10 in open-access papers (continued):
Sharing a sentence is not in itself a finding about the gene and the disease.
liver fibrosis (continued). "In this study, we found that liver injury and collagen deposition were reduced after CXCL10 neutralization in mice, which attenuated CCl4-induced liver fibrosis." (PMID 35484116, 2022). "It has been reported that CXCL10 plays a key role in wound healing, pulmonary fibrosis, and liver fibrosis." (PMID 35641484, 2022). "Since CXCL10 plays an important role in liver fibrosis pathogenesis, we examined the therapeutic value of CXCL10 neutralizing antibody in mouse models." (PMID 35484116, 2022). "A mouse model of liver fibrosis suggests that MyD88 signaling in activated HSCs promotes macrophage M1 polarization in a CXCL10/CXCR3-dependent manner, thus promoting liver fibrosis and inflammation." (PMID 37408838, 2022). "Levels of intrahepatic mRNA for CXCL10 and CXCR3 correlated with liver fibrosis and immunohistochemistry demonstrated CXCL10 expression in peri-portal hepatocytes." (PMID 32898182, 2020). "It has been shown that the IFN- γ inducible chemokines CXCL9, CXCL10, and CXCL11 are up-regulated in patients with chronic liver diseases, and their serum levels are closely associated with the degree of hepatic fibrosis." (PMID 32887613, 2020). "The polymorphisms in CXCL9 (monokine induced by interferon (IFN) γ), CXCL10 (IFN γ-inducible protein 10 (IP-10)), and CXCL11 (interferon-inducible T cell α chemoattractant; I-TAC) have been investigated in association with hepatic fibrosis." (PMID 32635162, 2020). "Deletion of CXCL10 inhibits murine liver fibrosis 19, and the neutralization of CXCL10 ameliorates experimentally induced liver injury in vivo 20,21." (PMID 32641985, 2020). "CXCL10-/- mice and WT mice treated with anti-CXCL10 antibody are protected from carbon tetrachloride-induced liver fibrosis." (PMID 33145014, 2020). "CXCL10 and its receptor CXCR3 have been implicated in fibrosis development in models of congenital hepatic fibrosis and carbon tetrachloride (CCl4)-mediated fibrosis." (PMID 31752395, 2019). "Collectively, these findings reveal hepatic MED23 as a key modulator of chemokine production and inflammatory responses and define the MED23-CCL5/CXCL10 axis as a potential target for clinical intervention in liver fibrosis." (PMID 31805036, 2019). "Higher expression of the chemokine interferon γ inducible protein 10 (IP-10/CXCL10) in liver and peripheral blood is described in patients with chronic HCV infection and are associated with liver fibrosis." (PMID 30507970, 2018). "In fact, CXCL10 should be considered more linkedto viral induced inflammation, while sCD163 and sCD14 more related to secondaryimmune events that lead to hepatic fibrosis." (PMID 28636655, 2017). "Given the fact that liver fibrosis is a marker of disease progression and severity and a consequence of active inflammation and liver injury, we examined the role of CXCL10 in FFC diet-induced NASH related fibrosis." (PMID 27349927, 2016). "Cytokines CXCL-11, INF-γ, and IL-17A are associated with liver inflammation, whereas CXCL-10, IL-2R, TGF-α, and IL-8 are correlated with liver fibrosis in chronic HBV-infected patients." (PMID 26559292, 2015). "Inhibition of CXCL10 attenuated macrophage M1 polarization and reduced liver fibrosis." (PMID 35484116, 2022). "Together, these data suggest that CXCL10 may be a promising therapeutic target for the prevention and treatment of liver fibrosis." (PMID 35484116, 2022). "It has been suggested that the HIV infection of hepatocytes in the presence of HBV could promote inflammation and flux of CXCL10 production, thus promoting the recruitment of activated CXCR3+ cells towards the liver that could cause liver fibrosis." (PMID 36366543, 2022). "Blocking or knocking out Cxcl10 in mice has been shown to attenuate CCl4-induced liver fibrosis." (PMID 35562519, 2022). "In case of chronic HCV infection, CXCL10 can be considered as a marker of liver fibrosis." (PMID 34531848, 2021).
liver fibrosis (continued). "Intrahepatic mRNA for CXCL10 and CXCR3 were both strongly associated with liver fibrosis on regression analysis for TE (η2 = 0.40, p<0.001 and η2 = 0.14, p = 0.026) and liver biopsy (odds ratio 1.10 (1.04, 1.16), p = 0.001, odds ratio 3.52 (1.33, 9.26), p = 0.011)." (PMID 32898182, 2020). "In addition, intrahepatic mRNA for CXCL10 and CXCR3 were also associated with liver fibrosis and inflammation." (PMID 32898182, 2020). "We hypothesised that CXCL10 will also play an important role in liver fibrosis in HIV-HBV co-infection." (PMID 32898182, 2020). "Our study demonstrated that hepatic RORα, in cooperation with MED23, plays a role in inflammatory responses, acting as a positive regulator of CCL5 and CXCL10 in initiating the liver fibrosis, which suggests new molecular targets for clinical intervention in liver fibrosis." (PMID 31805036, 2019). "Finally, DHA acting on HSCs also decreases inflammation by reducing the secretion of factors such as CXCL10, a pro-inflammatory chemokine that recruits leukocytes after liver injury and contributes to aHSC survival, migration and liver fibrosis development." (PMID 30622239, 2019). "Other papers, too, reported that in CHC, CXCL10 can be considered a marker of liver fibrosis." (PMID 31485460, 2019). "The CXCR3 ligands CXCL4, CXCL9 and CXCL10 seem to have divergent functions in liver fibrosis." (PMID 24646914, 2014). "By administering CXCL10 neutralizing antibody (Invitrogen, CA, USA) or an isotypic control (mIgG) preventively to the CCl4-treated mice, we found that CXCL10 neutralizing antibody significantly attenuates CCl4 induced liver fibrosis as indicated by reduced collagen deposition in whole liver lysate." (PMID 35484116, 2022). "In addition, CXCL10, which promotes liver fibrosis, was downregulated in TRIF−/− mice." (PMID 36289897, 2022). "In this study, we showed that lnc-Lfar1 silencing alleviated liver injury-induced upregulation of LY6C, IL-1β, IL-6, TNF-α, MCP-1, CCL5 and CXCL10 in vivo and in vitro, suggesting that lnc-Lfar1 knockdown might be beneficial for preventing liver fibrosis by targeting these chemokines." (PMID 32071306, 2020). "However, more samples from patients at different stages of liver fibrosis are required to determine whether the levels of CXCR3-associated chemokines, particularly CXCL10, are able to serve as biomarkers of liver disease severity in HCV/HIV-1 infection." (PMID 24516541, 2014). "Thus, this cluster may contribute to CXCL10-mediated liver fibrosis and activation of immune cells." (PMID 38436764, 2024). "In HIV and HBV co-infected patients, mRNA levels for CXCL10 and CXCR3 were correlated with liver fibrosis." (PMID 36366543, 2022). "CXCL9, CXCL10, and CXCL 16 attract lymphocytes or natural killer (NK) cells involved in hepatic inflammatory pathogenesis and accelerate hepatic fibrosis progression." (PMID 33603714, 2020). "We propose a model where HIV infection of hepatocytes in the presence of HBV and local inflammation drives an increase in CXCL10, recruiting activated CXCR3+ cells to the liver; establishing a cycle of inflammation leading to liver fibrosis." (PMID 32898182, 2020). "This study reveals that the transcriptional Mediator subunit MED23 regulates the pathogenesis of liver fibrosis by controlling the production of inflammatory cytokines such as CCL5 and CXCL10." (PMID 31805036, 2019). "The present study was to evaluate the predictive value of serum interferon gamma-inducible protein-10 (IP-10/CXCL10) and the interferon (IFN)-γ/interleukin (IL)-4 ratio for liver fibrosis progression in CHB patients." (PMID 28067328, 2017). "In a recent article published by our group, we found that CXCL9 rs10336 AA, CXCL10 rs3921 CC and CXCL11 rs4619915 AA genotypes were related to higher likelihood of severity of liver fibrosis in HIV/HCV-coinfected patients under a recessive model." (PMID 28755163, 2017).
liver fibrosis (continued). "In addition, we demonstrated that CXCL9 and CXCL10 suppressed the fibrosis associated gene expression in liver non-parenchymal cells and primary HSCs of mice in schistosomiasis and TGF-β -activated human hepatic stellate cells LX-2, suggesting their potential anti-fibrosis role in liver fibrosis." (PMID 22905138, 2012). "Finally, inflammatory plasma cytokine levels, namely of IFN‐γ, CXCL10, and TNF, were increased in CCl4‐treated mice at peak liver fibrosis, compared with oil controls." (PMID 40760842, 2025). "Furthermore, CXCL10 secreted from HSCs promotes macrophage M1 polarization via activating JAK/STAT1 pathway, which in turn promotes liver fibrosis." (PMID 35484116, 2022). "Our data agree with the models of fibrogenesis proposed by several authors where the activation of HSCs is the central event in hepatic fibrosis and shows that the number of α-SMA-positive HSCs mildly correlates with plasma levels of CXCL10 in AATD individuals enrolled in our study." (PMID 32887613, 2020). "Mechanistically, the orphan nuclear receptor RAR-related orphan receptor alpha (RORα) activates the expression of the liver fibrosis-related chemokines C-C motif chemokine ligand 5 (CCL5) and C-X-C motif chemokine ligand 10 (CXCL10), which is suppressed by the Mediator subunit MED23." (PMID 31805036, 2019). "Thus, the development of reagents to regulate the CXCL10/CXCR3 pathway, TNF-α and TGF-β may be useful therapeutic strategies to attenuate liver fibrosis." (PMID 36457551, 2022). "Meanwhile, expression of α-SMA was inhibited in LX-2 by CXCL9 but not CXCL10, suggesting the different function of CXCR3 associated chemokines in liver fibrosis and that the various chemokines might affect HSCs via non-chemokines receptors as other researchers reported." (PMID 22905138, 2012). "A series of reports have demonstrated that chemokine Interferon-γ Inducible protein 10 (IP-10, CXCL10) is a promising single marker correlate for liver fibrosis, and an IL-28b independent negative predictor of treatment outcome in HCV infected patients." (PMID 23024806, 2012).
pulmonary fibrosis (61 papers, 2005 to 2026). Chronic progressive interstitial lung disorder characterized by the replacement of the lung tissue by connective tissue, leading to progressive dyspnea, respiratory failure, or right heart failure. "Cxcl10-deficient mice show increased pulmonary fibrosis with enhanced fibroblast migration and lung accumulation." (PMID 39768150, 2024). "CXCL10 has been shown to act as a strong inhibitor of angiogenesis and has been implicated in the control of fibrosis in a mouse model of pulmonary fibrosis induced by bleomycin." (PMID 29127442, 2018). "Other studies have found that loss of γδ T cells enhances lung fibrosis, through loss of the anti-fibrotic mediators CXCL10, IL-22, and IFN-γ." (PMID 27649073, 2016). "CXCL10 deficient mice exhibit increased pulmonary fibrosis after bleomycin treatment while overexpression of CXCL10 in mice reduces fibroblast accumulation and fibrosis suggesting that CXCL10 acts as a protective cytokine in the lung." (PMID 27428020, 2016). "Interestingly, it was previously found that CXCL10 is expressed early in the disease and associated with a worse outcome, including more severe pulmonary fibrosis." (PMID 32508810, 2020). "Further investigation is required to understand the link between Tuj1-mediated signaling and Cxcl10 expression in activated pericytes in pulmonary fibrosis." (PMID 41472685, 2025). "This will provide therapeutic strategies to enhance the anti-fibrotic properties of lung pericytes, specifically by increasing CXCL10 expression, aiming to treat pulmonary fibrosis." (PMID 41472685, 2025). "Iloprost prevents pulmonary fibrosis, possibly by upregulating anti-fibrotic mediators (interferon γ and C-X-C motif chemokine ligand 10) and downregulating pro-inflammatory and pro-fibrotic cytokines (tumor necrosis factor α, IL-6, and TGF-β1)." (PMID 38878214, 2024). "Interaction between syndecan-4 and Cxcl10 in the lung interstitial compartment inhibits fibroblast recruitment and pulmonary fibrosis in mice." (PMID 39768150, 2024). "Recombinant Cxcl10 protein administration inhibits bleomycin-induced pulmonary fibrosis in mice, but this effect is abrogated in Sdc4-/- mice." (PMID 39768150, 2024). "Induced pluripotent stem cells (iPSCs) attenuate pulmonary fibrosis, neutrophil accumulation, and improve survival after bleomycin treatment by increasing antifibrotic Cxcl10 production in injured lungs." (PMID 39768150, 2024). "At present, the association between some cytokines and pulmonary fibrosis in SLE have been demonstrated, such as CXCL10, CXCL11, IL-8 and so on." (PMID 36871016, 2023). "For example, serum amyloid P (SAP) targets collagen deposition via stimulating the release of IP10/CXCL10 by M2 macrophages and ameliorates bleomycin-induced pulmonary fibrosis." (PMID 36232756, 2022). "The interplay between EZH2 and G9A in regulating CXCL10 transcription has also recently been observed in idiopathic pulmonary fibrosis by Coward and colleagues, further supporting our findings." (PMID 35131874, 2022). "Consistent with the results of in-vivo studies, serum CXCL10 level was markedly higher in patients with idiopathic pulmonary fibrosis than in control subjects." (PMID 35432206, 2022). "Combined with elevated SASP mRNA expression (including Ccl2, Cxcl10, Ccl17, Mmp2, Mmp9, and Mmp12) in sorted macrophages after irradiation, we confirmed that senescent macrophages were partly contributed to lung fibrosis." (PMID 34023858, 2021). "CXCL10 was used to alleviate fibrosis disease, such as bleomycin-induced pulmonary bleomycin-induced pulmonary fibrosis, and p-Cav-1 was also reported to be key player in the process of fibrosis." (PMID 34790658, 2021).
pulmonary fibrosis (continued). "While CXCL10 has profibrotic effects in the liver, CXCL10 limits lung fibrosis in the murine model of bleomycin-induced pulmonary fibrosis." (PMID 33145014, 2020). "CXCR3-/- and CXCL10-/- mice display exaggerated pulmonary fibrosis after bleomycin administration, and transgenic mice overexpressing CXCL10 are protected from bleomycin-induced mortality." (PMID 33145014, 2020). "The TARC (CCL17)/IP-10 (CXCL10) ratio was described as a marker for fibrogenesis in the lung in patient with usual interstitial pneumonia and subsequent idiopathic pulmonary fibrosis." (PMID 26807786, 2016). "CXCL10/IP-10, which is regulated by the antifibrotic factor IFNγ, has been shown to attenuate bleomycin-induced pulmonary fibrosis in mice via inhibition of fibroblast recruitment or of angiogenesis." (PMID 20302663, 2010). "Iloprost prevents bleomycin-induced pulmonary fibrosis, possibly by upregulating antifibrotic mediators (IFNγ and CXCL10) and downregulating pro-inflammatory and pro-fibrotic cytokines (TNFα, IL-6, and TGFβ1)." (PMID 20302663, 2010). "Because of the role of CXCR3 expression in the migration of T cells, strategies to block CXCL10 could in theory be proposed to prevent the development of HP reactions, particularly in subjects continuously exposed to inhaled antigens and thus at risk for the development of lung fibrosis." (PMID 15725351, 2005). "In a bleomycin-induced pulmonary fibrosis mouse model, Cxcl10 is highly expressed." (PMID 39768150, 2024). "C1qa, Fcgr1, C1qb, C1qc, Ccr5, Slc11a1, Aif1, Emr1 and Cxcl10 were identified as the most closely connected module which were highlighted in yellow, including 9 nodes and 32 edges, and the genes in this region were upregulated in pulmonary fibrosis." (PMID 35078421, 2022). "The CXCL10 knockout mice also showed increased pulmonary fibrosis." (PMID 33879231, 2021). "Indeed, severe and moderate PC patients with lung fibrosis-like changes had higher levels of CXCL10 than healthy subjects (pink and blue dots)." (PMID 34944747, 2021). "Tuj1-expressing pericytes localize near SPP1+/arginase+ macrophages and express high levels of CXCL10, a chemokine that suppresses the pro-fibrotic macrophage differentiation, suggesting that this pericyte population contributes to counteracting the progression of pulmonary fibrosis." (PMID 41472685, 2025). "In SLE, Nielepkowicz-Goździńska A and others found that CXCL10 and CXCL11 are associated with the accumulation of neutrophils in the alveolar spaces of patients with SLE lung fibrosis, potentially contributing to interstitial fibrosis, providing some support for our hypothesis." (PMID 39185418, 2024). "Several recent publications have shown grounds for promise in identifying additional blood and tissue biomarkers, such as IL-1β, CXCL10, Eotaxin-3, PARC and IgE, in both COPD and pulmonary fibrosis." (PMID 41157273, 2025). "Multiple studies have shown that chemokines such as CXCL9, CXCL10, and CXCL11 promote pulmonary fibrosis by recruiting fibrosis-related macrophages, but the role of CXCL14 in IPF has long been overlooked." (PMID 40842541, 2025). "In patients with pulmonary fibrosis, increased levels of CXCL9, CXCL10, CCL18, CTO, and CA15.3 are accompanied by elevated SP-D, a component of lung surfactant and a pattern-recognition molecule produced by alveolar type II cells and Clara cells." (PMID 37445972, 2023). "While there is limited evidence on the role of SDC4 in cancer, it has been shown that interaction between CXCL10 and SDC4 inhibits fibroblast recruitment in pulmonary fibrosis." (PMID 34430923, 2021).